CEBPA (CCAAT enhancer binding protein alpha)
Description:
Transcription factor that coordinates proliferation arrest and the differentiation of myeloid progenitors, adipocytes, hepatocytes, and cells of the lung and the placenta. Binds directly to the consensus DNA sequence 5'-T[TG]NNGNAA[TG]-3' acting as an activator on distinct target genes. During early embryogenesis, plays essential and redundant functions with CEBPB. Essential for the transition from common myeloid progenitors (CMP) to granulocyte/monocyte progenitors (GMP). Critical for the proper development of the liver and the lung (By similarity). Necessary for terminal adipocyte differentiation, is required for postnatal maintenance of systemic energy homeostasis and lipid storage (By similarity). To regulate these different processes at the proper moment and tissue, interplays with other transcription factors and modulators. Down-regulates the expression of genes that maintain cells in an undifferentiated and proliferative state through E2F1 repression, which is critical for its ability to induce adipocyte and granulocyte terminal differentiation. Reciprocally E2F1 blocks adipocyte differentiation by binding to specific promoters and repressing CEBPA binding to its target gene promoters. Proliferation arrest also depends on a functional binding to SWI/SNF complex. In liver, regulates gluconeogenesis and lipogenesis through different mechanisms. To regulate gluconeogenesis, functionally cooperates with FOXO1 binding to IRE-controlled promoters and regulating the expression of target genes such as PCK1 or G6PC1. To modulate lipogenesis, interacts and transcriptionally synergizes with SREBF1 in promoter activation of specific lipogenic target genes such as ACAS2. In adipose tissue, seems to act as FOXO1 coactivator accessing to ADIPOQ promoter through FOXO1 binding sites (By similarity). [Isoform 3]: Can act as dominant-negative. Binds DNA and have transctivation activity, even if much less efficiently than isoform 2. Does not inhibit cell proliferation. [Isoform 4]: Directly and specifically enhances ribosomal DNA transcription interacting with RNA polymerase I-specific cofactors and inducing histone acetylation.
Synonyms: CEBP; C/EBP-alpha
Tractability: PROTAC: UniProt records ubiquitination sites on it; ubiquitination databases record sites on it.
Gene: Protein-coding gene on chromosome 19 (33,299,934 to 33,302,534, reverse strand). Ensembl gene ENSG00000245848.
Subcellular location: Nucleus; Nucleus, nucleolus (Isoform 4)
Subcellular location (Human Protein Atlas): Nucleoplasm; Vesicles
Pathways (Reactome):
Developmental Biology: Transcriptional regulation of granulopoiesis; Transcriptional regulation of white adipocyte differentiation
Gene expression (Transcription): MLL4 and MLL3 complexes regulate expression of PPARG target genes in adipogenesis and hepatic steatosis
Gene Ontology:
Molecular function: DNA-binding transcription activator activity, RNA polymerase II-specific; DNA-binding transcription factor activity; identical protein binding; kinase binding; protein binding; RNA polymerase II-specific DNA-binding transcription factor binding; STAT family protein binding; transcription cis-regulatory region binding; DNA binding; DNA-binding transcription factor activity, RNA polymerase II-specific; protein homodimerization activity; RNA polymerase II cis-regulatory region sequence-specific DNA binding; chromatin binding; chromatin DNA binding; DNA-binding transcription factor binding; HMG box domain binding; protein heterodimerization activity; sequence-specific DNA binding
Biological process: interleukin-6-mediated signaling pathway; negative regulation of cell population proliferation; positive regulation of transcription by RNA polymerase II; regulation of DNA-templated transcription; cytokine-mediated signaling pathway; energy homeostasis; fat cell differentiation; generation of precursor metabolites and energy; glucose homeostasis; granulocyte differentiation; integrated stress response signaling; lipid homeostasis; liver development; lung development; myeloid cell differentiation; negative regulation of DNA-templated transcription; positive regulation of inflammatory response; positive regulation of macrophage activation; positive regulation of proteasomal ubiquitin-dependent protein catabolic process; regulation of cell cycle; regulation of transcription by RNA polymerase II; white fat cell proliferation; DNA-templated transcription; negative regulation of cell cycle; negative regulation of transcription by RNA polymerase II; and 1 more
Cellular component: C/EBP complex; CHOP-C/EBP complex; nucleoplasm; nucleus; RNA polymerase II transcription regulator complex; transcription regulator complex; chromatin; nucleolus
Genetic constraint (gnomAD): Loss-of-function variants: 2 observed, 4.47 expected, observed/expected ratio (o/e) 0.45, 90% interval 0.18 to 1.37. That is too few expected variants to judge how well the gene tolerates losing a copy. Missense variants: 417 observed, 353.26 expected, observed/expected ratio (o/e) 1.18, 90% interval 1.09 to 1.28. Synonymous variants: 249 observed, 175.48 expected, observed/expected ratio (o/e) 1.42, 90% interval 1.28 to 1.58.
Gene-disease validity (ClinGen):
ClinGen rates the evidence that CEBPA causes each of these diseases.
acute myeloid leukemia (autosomal dominant): Definitive. Acute myeloid leukemia (AML) is a group of neoplasms arising from precursor cells committed to the myeloid cell-line differentiation.
Cancer hallmarks: suppression of growth (promotes); change of cellular energetics (promotes); proliferative signalling (promotes); escaping programmed cell death (promotes); escaping programmed cell death (suppresses); invasion and metastasis (promotes); invasion and metastasis (suppresses)
Homologues: Orthologues: pig CEBPA (96% identical), rabbit CEBPA (95% identical), mouse Cebpa (94% identical), rat Cebpa (94% identical), tropical clawed frog cebpa (49% identical), zebrafish cebpa (49% identical), Caenorhabditis elegans zip-4 (16% identical), Caenorhabditis elegans cebp-1 (15% identical), Drosophila melanogaster slbo (15% identical). Paralogues in human: CEBPE (35% identical), CEBPB (30% identical), CEBPD (29% identical), CEBPG (13% identical).
Diseases named in the same sentence as CEBPA in open-access papers:
CEBPA is named in the same sentence as 262 diseases in open-access papers, as found by Europe PMC text mining. Sharing a sentence is not in itself a finding about the gene and the disease. The quoted sentences say what the papers report.
Obesity (190 papers, 2010 to 2026). Accumulation of substantial excess body fat. "CEBPα regulates transcription of the human fat mass and obesity-associated gene (FTO), and c-MYC is well known for its role in cancer metabolism." (PMID 26109058, 2015). "It represses the induction of critical adipogenic regulators, such as PPARγ and CCAAT/enhancer-binding protein alpha (CEBPA), providing a pathway for potential genetic obesity therapies." (PMID 39684593, 2024). "During unhealthy obesity, the hypertrophic adipocytes are characterized by reduced PPARγ and CEBPa (this report and87) which indicates an inhibition of the adipogenesis in the WAT of morbidly patients with obesity undergoing bariatric surgery." (PMID 38677183, 2024). "Accordingly, PPARγ and CEBPα are extensively utilized as targets for the development of anti-obesity drugs through the inhibition of adipogenesis, both in vitro and in vivo." (PMID 39210615, 2024). "In line with this, a decreased expression of PPARγ, CEBPα, and LXRα in adipose tissue of women with obesity can reflect low adipose tissue expansion in the present study." (PMID 37106328, 2023). "Currently, drugs from natural sources that specifically inhibit peroxisome proliferator-activated receptor gamma (PPARγ) and CCAAT enhancer-binding protein alpha (C/EBPα) expression are being targeted for the treatment of obesity." (PMID 35208957, 2022). "The overexpression of miR-144 increased lipid accumulation and promoted adipogenesis while levels of CCAAT-enhancer binding protein alpha (C/EBPα) were also upregulated in the murine model of obesity." (PMID 34690698, 2021). "We found captured, MVAs expressed significantly higher levels of TNFA, CEBPA, and KLF2 transcripts than MSA, all of which favor reduced levels of adipogenesis in VAT and higher levels of RETN and SERPINs, which are linked to obesity-related disease risk." (PMID 27462403, 2016). "We next considered whether the HVRs were enriched for either the occupancy of three specific transcription factors (HNF4A, CEBPA, and FOXA1) or the 418 rat orthologues of Human GWAS variants associated with obesity and metabolic traits." (PMID 29272997, 2017). "Thus altogether, in our study effects of Se on PPARγ and CEBPα expression could indicate a restoration of epididymal fat adipocyte metabolic function during obesity." (PMID 35624758, 2022). "For instance, in obesity models, NAT10 knockdown reduces ac4C modification on KLF9 mRNA, destabilizes its transcripts, and suppresses downstream CEBPA/B-PPARG pathway activity, thereby inhibiting adipogenesis and alleviating high-fat diet-induced obesity." (PMID 40588654, 2025). "Firstly, we detected expression levels of key adipogenesis genes, such as CEBPA, PPARG, lipoprotein lipase (LPL), fatty acid binding protein 4(FABP4) and perilipin 1 (PLIN1), which play critical roles in the development of obesity." (PMID 39773638, 2025). "KLF15, CEBPA, and CEBPB are crucial for the early stages of adipocyte differentiation, and their downregulation in ASCs may reflect a shift away from adipogenic potential as obesity progresses." (PMID 40518865, 2025). "Obesity and nutritional factors influence the expression of PPARγ in human adipocytes and the existence of conditions, such as type two diabetes, once the expression of PPARγ and CEBPA is related negatively to fat cell size in non-obese men with type two diabetes." (PMID 36676057, 2022).
acute myeloid leukemia (166 papers, 2006 to 2026). "Mutations or abnormal expression of CEBPA are associated with various diseases, particularly in acute myeloid leukemia (AML), where its mutation is considered a disease-driving factor." (PMID 41142795, 2025). "Mutations of the gene encoding the CCAAT-enhancer binding protein alpha (CEBPA) transcription factor are common genetic alterations in acute myeloid leukemia (AML)." (PMID 38228680, 2024). "Supporting these findings are reports showing that CEBPA knockdown decreases Chaf1a expression, and that patients with acute myeloid leukemia that have CEBPA double mutations have decreased Chaf1a levels." (PMID 38392328, 2024). "Mutations within the CEBPA gene selectively deleting p42 are frequent in human acute myeloid leukemia." (PMID 37532789, 2023). "CCAAT enhancer binding protein A (CEBPA) gene mutation is one of the common genetic alterations in acute myeloid leukemia (AML), which can be associated with sporadic and familial AML." (PMID 37261703, 2023). "TET2 and GATA2 are two frequently co-mutated genes in CEBPA double mutated acute myeloid leukemia (AML)." (PMID 37794021, 2023). "CEBPA mutations are one of the most frequent genetic lesions in patients with acute myeloid leukemia (AML)." (PMID 35178345, 2022). "Approximately 30% of Chinese individuals with cytogenetically normal acute myeloid leukemia (CN-AML) have biallelic CEBPA (biCEBPA) mutations." (PMID 34485141, 2021). "The intronless CEBPA gene is mutated in approximately 10-15% of human acute myeloid leukemia (AML) cases." (PMID 34189442, 2021). "This study aimed to investigate the correlation between GM-CSF gene expression and different molecular prognostic markers such as FLT3-ITD, NPM1 mutation A and CEBPA gene expression in Egyptian acute myeloid leukemia patients." (PMID 32711425, 2020). "The CCAAT/enhancer binding protein α (CEBPA) gene is mutated in 9% of acute myeloid leukemia samples, and C/EBPα p30 is the most common type of CEBPα mutation." (PMID 30488017, 2018). "Mutations in the CCAAT/enhancer binding protein α (CEBPA) gene occur in 7%–15% of all acute myeloid leukemia (AML) cases." (PMID 29861846, 2018). "Upregulation of CEBPA has been linked to favorable prognosis in both adult and pediatric acute myeloid leukemia patients." (PMID 26496024, 2016). "CCAAT enhancer-binding protein-α (C/EBPα) is another tumor suppressor that can inhibit cell proliferation, and mutations in CEBPA are widely reported in acute myeloid leukemia (AML) patients." (PMID 24598081, 2014). "In fact, the initial version of SNPExpress has already been successfully applied in showing segmental uniparental disomy as a recurrent mechanism for homozygous CEBPA mutations in acute myeloid leukemia." (PMID 18221515, 2008). "The CEBPA transcription factor is frequently mutated in acute myeloid leukemia (AML)." (PMID 40221437, 2025). "CCAAT/enhancer binding protein alpha (CEBPA) alterations are more prevalent in hematologic malignancies, where CEBPA mutations have been associated with improved outcomes in pediatric and adult acute myeloid leukemia." (PMID 38164123, 2024). "Mutations in the CEBPA gene are present in 10–15% of acute myeloid leukemia (AML) patients." (PMID 31867767, 2020). "We show that for acute myeloid leukaemias with CEBPA mutations, the dependency of leukaemia growth and differentiation on the Myb transcription factor is related to the combination of N- and C-terminal mutations involved and how this affects overall gene expression." (PMID 30877232, 2019). "Mutation in the CEBPA gene has been linked to acute myeloid leukemia." (PMID 32038705, 2019). "In addition, miR-182 expression is highly elevated particularly in acute myeloid leukemia patients with C-terminal CEBPA mutations, thereby depicting a mechanism by which C/EBPα blocks miR-182 expression." (PMID 28663557, 2017). "CEBPA mutations are found in 5 - 14% of acute myeloid leukemia (AML) cases." (PMID 20398252, 2010).
acute myeloid leukemia (continued). "CEBPA-associated familial acute myeloid leukemia (AML) is an autosomal dominant leukemia predisposition syndrome associated with germline variants in the CEBPA gene." (PMID 40313597, 2025). "CEBPA-associated familial acute myeloid leukemia (AML) is an autosomal dominant predisposition to AML confered by germline (likely) pathogenic variant affecting the N-terminal extremity of the protein (upstream of the codon 120)." (PMID 40313597, 2025). "Mutations in nucleophosmin 1 (NPM1), FMS-like tyrosine kinase 3 (FLT3) and CCAAT/enhancer-binding protein α (CEBPA) contribute to risk stratification of cytogenetically normal acute myeloid leukemia (CN-AML)." (PMID 39767827, 2024). "Results of different studies that evaluated the effect of CCAAT Enhancer Binding Protein Alpha (CEBPA) mutations in clinical outcomes of pediatric acute myeloid leukemia (AML) patients." (PMID 35967564, 2022). "Mutations in CCAAT enhancer binding protein A gene (CEBPA) are one of the common genetic alterations in acute myeloid leukemia (AML)." (PMID 35178345, 2022). "Adult acute myeloid leukemia (AML) patients with biallelic mutations of CEBPA (biCEBPA) displays a favorable clinical outcome, and is defined as a unique entity in the 2016 World Health Organization classification." (PMID 34513657, 2021). "Within the hematopoietic system, inactivation mutation of CEBPA blocks the granulocytic differentiation in acute myeloid leukemia (AML)." (PMID 34178023, 2021). "Mutations in the CEBPA gene have been described in around 10% of acute myeloid leukemia (AML), establishing a tumor suppressor role of C/EBPα in cancer development." (PMID 32034145, 2020). "On the other hand, 10–15% of sporadic acute myeloid leukemia with normal karyotype (NK-AML) presents the somatic CEBPA mutations." (PMID 28955657, 2017). "CEBPA is frequently mutated in acute myeloid leukemia (AML), but the transcriptional impact of the AML-associated isoform remains unclear." (PMID 40221437, 2025). "Kovecses and colleagues reveal that targeted delivery of small activating RNAs restores CEBPA expression in acute myeloid leukemia, enhancing sensitivity to FLT3 inhibition and reducing leukemic burden." (PMID 40686853, 2025). "It is confirmed that CEBPA plays an important role in the proliferation and differentiation of a myeloid progenitor, and its biallelic mutation is highly related to acute myeloid leukemia (AML)." (PMID 37333458, 2023). "Mutated CEBPA is an important prognostic marker in acute myeloid leukemia (AML)." (PMID 37261703, 2023). "Two concurrent mutational signatures in CSF3R (Colony Stimulating Factor 3 Receptor) and CEBPA (CCAAT Enhancer Binding Protein Alpha) that are related to higher relapse rates have been identified in patients with acute myeloid leukemia." (PMID 36295546, 2022). "Biallelic CEBPA (biCEBPA) mutations are detected in 2-15% of de novo acute myeloid leukemia (AML) patients, and are associated with a favorable clinical outcome compared to wildtype or monoallelic CEBPA mutation." (PMID 34513657, 2021). "In acute myeloid leukemia patients, EZH2 mutations frequently co-occurred with CEBPA (67%), ASXL1 (50%), TET2 and RAD21 mutations (33% each)." (PMID 33845873, 2021). "The CEBPA promoter is aberrantly methylated in ~30% and ~51% of patients with chronic myeloid leukemia and acute myeloid leukemia, respectively." (PMID 34831209, 2021). "Others loci are associated with hematological disorders such as CEBPA, FOXP1, MECOM and RHOH which promotes Acute myeloid leukemia, diffuse large B-cell lymphoma, myeloproliferative neoplasm and B-cell chronic lymphocytic leukemia respectively." (PMID 31105870, 2019). "When comparing the results of CEBPA expression with patients suffering from acute myeloid leukemia, ALL cases showed statistically significant lower levels of CEBPA (P < 0.0000)." (PMID 31666608, 2019).